MAG (myelin associated glycoprotein)
Diseases named in the same sentence as MAG in open-access papers (continued):
Sharing a sentence is not in itself a finding about the gene and the disease.
neuropathy (continued). "As anti-MAG neuropathy is the most common disabling paraproteinemic neuropathy and since the anti-MAG antibodies appear to exert a direct pathogenic effect on the myelin structure and function, B cells depleting therapies have been the main therapeutic mode of treatment." (PMID 36672019, 2022). "In addition, anti-myelin associated glycoprotein (anti-MAG) neuropathy, a chronic sensorimotor demyelinating polyneuropathy is another entity in which rituximab has been tested." (PMID 33530460, 2021). "Furthermore, in vivo data clearly demonstrate the efficient removal of pathogenic anti‐MAGs in a mouse model for anti‐MAG neuropathy." (PMID 33752265, 2021). "Anti-myelin-associated glycoprotein (MAG) Abs are detectable by ELISA in half of IgM paraproteinemic neuropathy cases; they identify a pathognomonic clinical picture characterized by a sensory ataxic demyelinating neuropathy with neuropathic tremor and a slow progression." (PMID 34439911, 2021). "Pathological studies in neuropathy with anti-MAG antibodies reveals demyelination in association with widening of myelin lamellae on electron microscopic examination along with deposits of IgM and complement on myelin sheaths as demonstrated by direct immunohistochemistry." (PMID 30264176, 2019). "Moreover, consensus diagnostic criteria for anti-MAG neuropathy have been published and mostly rely on this feature along with severe reduction of SNAPs." (PMID 26065001, 2015). "As GD3 does not bind to myelin-associated glycoprotein (MAG), a key mediator of myelin stability, and GM3 binds poorly to myelin-associated glycoprotein, these mice have defective axon:myelin stability leading to progressive neuropathy, similar to that seen in MAG-deficient mice." (PMID 24103911, 2013). "Other studies suggest that lenalidomide, a drug that is associated with a lower level of toxicity than thalidomide and which is primarily employed in the treatment of multiple myeloma, might theoretically confer benefits in the management of anti-myelin-associated glycoprotein neuropathy." (PMID 40649805, 2025). "The features observed in all patients associated with MAG mutations included ataxia (20/20), developmental delay (12/20), dysarthria (12/20), nystagmus (16/20), spasticity (15/20), pyramidal signs (13/20), hyporeflexia (12/20), delayed gait (10/20), and neuropathy (10/20)." (PMID 39336794, 2024). "In addition, genetic markers such as FcγRIIIA polymorphisms in anti-MAG neuropathy and FCGR3A polymorphisms in NMO or generally studying the B cell receptor repertoire may prove to be of value." (PMID 35182380, 2022). "Additionally, the similarity of some of the BNS symptoms to the symptoms observed in other complications of WM, e.g., hyperviscosity syndrome or neuropathy related to anti-myelin associated glycoprotein (MAG) antibodies, makes the diagnosis even more challenging for physicians." (PMID 35956064, 2022). "In addition, preclinical evidence has shown that ibrutinib effectively ameliorates disease symptoms in patient samples or animal models of SLE, MS, systemic sclerosis (SSc), neuropathy with anti-myelin-associated glycoprotein (MAG), type 2 diabetes (T2D) and obesity." (PMID 34778053, 2021). "However, the association of anti-MAG antibodies with neuropathy is already established." (PMID 33136178, 2021). "Besides its diagnostic role, sural nerve biopsy has helped understand the pathogenesis of several neuropathies, first of all, the most common immune-mediated neuropathy, that is the neuropathy with antibodies to the myelin-associated glycoprotein (anti-MAG neuropathy)." (PMID 33498362, 2021). "Moreover, case reports have emphasized that a motor phenotype of anti-MAG associated neuropathy could be linked to a good response to IVIg." (PMID 26065001, 2015). "A second study from Japan explored the role of tirabrutinib, a second-generation BTK inhibitor, for anti-MAG neuropathy." (PMID 40351903, 2025).
neuropathy (continued). "Anti ‐ MAG antibody neuropathy shows more homogenous nerve enlargement, tends to affect distal nerves more while in CIDP there are more noticeable fascicular changes with or without nerve enlargement." (PMID 40542608, 2025). "There is a class IV evidence study showing that BTK inhibitors can improve anti-MAG-related neuropathy." (PMID 40351903, 2025). "Anti-MAG antibodies are generally observed in patients with chronic gait disturbances and neuropathy, although the ataxia arises from central nervous system involvement." (PMID 40881707, 2025). "IgM entities contributing to neuropathy include anti-MAG neuropathy, AL amyloidosis, and cryoglobulinemia as well as, infrequently, WM infiltration into the central nervous system (Bing–Neel syndrome)." (PMID 41300976, 2025). "Emerging clinical data indicate that BTK inhibitors show therapeutic potential in the treatment of patients affected by anti-MAG antibody neuropathy, as evidenced by observations within studies of WM patients." (PMID 40351903, 2025). "One study showed improvement in anti-MAG antibody polyneuropathy with ibrutinib in three patients with anti-MAG neuropathy." (PMID 40351903, 2025). "Regardless of the underlying haematologic condition, however, the literature indicates that at least 60% of individuals with anti-MAG neuropathy respond to rituximab (RTX), an anti-CD20 monoclonal antibody." (PMID 41031196, 2025). "CIDP responds to immunoglobulin, corticosteroids, and plasma exchange, whereas anti-MAG antibody neuropathy generally responds better to anti-CD20 monoclonal antibodies such as rituximab [3▪,33▪▪]." (PMID 40748018, 2025). "Methods: 4 CIDP and 4 anti‐MAG neuropathy patients were selected for detailed nerve ultrasound analysis, performed by single trained expert in nerve ultrasound." (PMID 40542608, 2025). "To the best of our knowledge, we believe this to be the first reported use of zanubrutinib to treat anti-MAG neuropathy after refractory responsiveness to rituximab, excluding clinical trials." (PMID 40351903, 2025). "This clinical vignette highlights the outcomes of zanubrutinib in the management of anti-MAG antibody neuropathy in a patient with WM." (PMID 40351903, 2025). "Distal neuropathy with an IgM paraprotein and anti-MAG antibodies, anti-MAG neuropathy, is considered outside the span of CIDP as most of these patients have specific electrodiagnostic and pathologic findings and do not respond to IVIg or corticosteroids." (PMID 39897200, 2025). "Distinguishing CIDP from anti-MAG antibody neuropathy carries important prognostic and therapeutic implications." (PMID 40748018, 2025). "Anti-MAG neuropathy is characterized by IgM immunoreactivity to MAG antigens on central and peripheral myelin, leading to paresthesia and discomfort." (PMID 40351903, 2025). "We translated the treatment strategy used in NMOSD to anti-MAG neuropathy based on their biosimilarity as B-cell–mediated autoimmune diseases driven by pathogenic autoantibodies." (PMID 41031196, 2025). "Several risk factors have been identified for the worsening prognosis of anti-MAG neuropathy, such as a demyelinating pattern and older age." (PMID 40351903, 2025). "RTX effectively targets B cells in both conditions, supporting the rationale for CD27+ B-cell monitoring in anti-MAG neuropathy, similarly to its well-established use in NMOSD." (PMID 41031196, 2025). "Up to 50–65% of patients with a “DADS phenotype” neuropathy and IgM monoclonal gammopathy have IgM antibodies with anti-MAG activity." (PMID 39555481, 2024). "In our systematic review of the literature, we identified clinical cases of acute neurological worsening in patients with anti-MAG neuropathy after Rituximab therapy by conducting a comprehensive search in PubMed, Scopus and Cochrane." (PMID 39766493, 2024).
neuropathy (continued). "Taken together, adequate VTE prophylaxis in this patient population warrants particular attention should lenalidomide carry any potential future viability as a therapeutic consideration for anti‐MAG neuropathy." (PMID 38015467, 2024). "Previous studies have shown that Rituximab is ineffective in 30–50% of patients with anti-MAG neuropathy." (PMID 39766493, 2024). "In a recent study, cut-offs of >1,000 BTU, >1,500 BUT and > 7,000 BTU were associated with a sensitivity of 100, 100 and 92.5% respectively, and a specificity of 90.99, 95.5 and 100%, respectively, to diagnose anti-MAG neuropathy." (PMID 39555481, 2024). "With this technique, anti-HNK1 MAG antibody titers appear to correlate with the severity of neuropathy." (PMID 39555481, 2024). "In this case, the coexistence of anti‐MAG neuropathy represented a concern for the use of bortezomib." (PMID 38662353, 2024). "We found 13 previously reported cases of acute neurological worsening after Rituximab therapy in patients with anti-MAG neuropathy." (PMID 39766493, 2024). "We present a case of an IgM flare in a patient with anti-MAG neuropathy following Rituximab treatment." (PMID 39766493, 2024). "No proven effective or US Food and Drug Administration (FDA)‐approved therapies exist for anti‐MAG neuropathy." (PMID 38015467, 2024). "These have shown promising results in a subgroup of patients with both anti-MAG neuropathy and Waldenström’s disease, specifically those with the MYD88 L265P mutation and wild-type CXCR4." (PMID 39766493, 2024). "Some data are available for fascicle CSA (f-CSA) in CIDP7 but, to our knowledge, little is known about changes occurring at the level of the fascicle in d-CIDP and anti-MAG neuropathy." (PMID 38409319, 2024). "To this end, we analysed the nerve and fascicle CSA in patients with CIDP, d-CIDP and anti-MAG neuropathy." (PMID 38409319, 2024). "We also considered the possibility of neuropathies mediated by anti-MAG antibodies or anti-ganglioside antibodies." (PMID 39310528, 2024). "For these reasons we aimed to assess the safety and optimal dose of lenalidomide in anti‐MAG neuropathy as well as to explore therapeutic efficacy." (PMID 38015467, 2024). "Anti-MAG antibody neuropathy is the most common IG M paraproteinemic neuropathy characterized by predominant sensory symptoms, ataxic gait, tremor upper limb with motor involvement and disability occurring late in the course of the disease." (PMID 37298132, 2023). "In CIDP, rheobase is known to be increased and SDTC to be decreased, while no such changes have been previously reported in patients with anti-MAG neuropathy and CMT1." (PMID 37899433, 2023). "Rituximab a chimeric monoclonal antibody against CD 20 +B lymphocytes has been assessed in two randomized controlled trials and nowadays is the most used in anti-MAG antibody neuropathy treatment." (PMID 37298132, 2023). "A distal neuropathy accompanied by an IgM paraprotein and anti-MAG antibodies, known as anti-MAG neuropathy, is considered distinct from CIDP." (PMID 38138263, 2023). "Anti-MAG neuropathy occurs when antibodies attack MAG proteins, and this type of neuropathy is observed in about 5% of patients with CIDP-like features." (PMID 37108447, 2023). "Other parameters, such as a modified F-ratio or residual latency, can help to distinguish anti-MAG neuropathy from CIDP." (PMID 36672019, 2022). "Chronic dysimmune antibody-related neuropathies include anti-MAG neuropathy, multifocal motor neuropathy, and neuropathies related to immune attack against paranodal antigens." (PMID 36672019, 2022). "The correct diagnosis of anti-MAG neuropathy is essential first to the treatment choice and to ensuring an accurate hematological follow-up in these patients as well." (PMID 36672019, 2022). "Patients with anti-MAG neuropathy treated with rituximab have seen clinical benefit, reduction of anti-IgM and anti-MAG antibodies, and Treg upregulation." (PMID 35182380, 2022).
neuropathy (continued). "Although transient worsening of the neuropathy was noted in a minority of patients, clinical improvements occurred in over 30% and were more common in patients who had a reduction in Anti MAG titres." (PMID 35756635, 2022). "Among the patients with inflammatory neuropathy, adherence to vaccination was comparable to other groups, although those with anti-MAG neuropathy reported a lower adherence (n = 4/6, 66.7% vs. 254/262, 97%; Fisher’s exact test: p = 0.017)." (PMID 36291329, 2022). "A terminal latency index (TLI) of 0.26 in the median nerve and 0.33 in the ulnar nerve represents the threshold values for distinguishing anti-MAG neuropathy from CIDP-MAG." (PMID 36672019, 2022). "In a small number of patients with anti-MAG neuropathy, clinical improvement with rituximab appears to coincide with the reduction in total and MAG IgM, possibly attributed to depletion of memory cell precursors of short-lived antibody secreting cells." (PMID 35182380, 2022). "In patients with IgM anti-MAG neuropathy, RTX mitigated pain and paresthesia through T reg cell activation, and in patients with multiple sclerosis, B-cell depletion caused inactivation of Th-cell activity in an autoantibody-independent manner." (PMID 35496906, 2022). "Neuropathy with anti-MAG antibodies is the most common IgM paraproteinemic neuropathy, characterized by predominant sensory symptoms, ataxic gait, tremor at upper limbs, with motor involvement and disability occurring late in the course of the disease." (PMID 35349079, 2022). "According to EFNS/PNS recommendation, the authors suggest considering IVIg treatment in patients with anti-MAG neuropathy clinically similar to typical CIDP." (PMID 36672019, 2022). "Albeit with low-quality evidence, a Cochrane meta-analysis confirmed that rituximab improves disability scales and the response to questionnaires in the global impression of anti-MAG antibody neuropathy." (PMID 35326711, 2022). "The BTK inhibitors (ibrutinib, zanubrutinib, rilzabrutinib) have a potential therapeutic role in B-cell-mediated diseases other than anti-MAG antibody neuropathy, given their good profile (oral administration and favorable safety profile)." (PMID 35349079, 2022). "In another series, progression to WM or amyloidosis was observed in 3 out of 22 patients with anti-MAG neuropathy." (PMID 34680279, 2021). "A relevant epitope in anti-MAG neuropathy is the HNK-1 (human natural killer-1) that is located in the peripheral nervous system." (PMID 34680279, 2021). "Regarding anti-MAG neuropathy, the description of its clonal genomic status gives more argument for using Bruton Tyrosine Kinase inhibitors in this group of patients." (PMID 34680279, 2021). "We discuss the potential role of anti-MAG antibodies in the pathophysiology of dorsal column impairment and the clinical usefulness of SSEPs in monitoring the evolution of anti-MAG neuropathy." (PMID 32397154, 2020). "A prospective single-arm trial of ten patients with anti-MAG IgM-related neuropathy found all patients to have improved after 375 mg/m2 rituximab monotherapy every four weeks for twelve months." (PMID 32545521, 2020). "A randomized, placebo-controlled trial of rituximab in IgM MGUS patients with neuropathy and anti-MAG antibodies showed benefit in one-third of the treatment arm compared to stable disease or worsening symptoms in the placebo arm." (PMID 32545521, 2020). "Situated in the plasma membrane with the hydrophilic carbohydrate moiety exposed extracellularly, gangliosides have a greater propensity for autoimmune reaction, especially in GBS, CIDP, and anti- MAG neuropathy." (PMID 30941082, 2019). "Initially, she was thought to have monoclonal gammopathy of undetermined significance (MGUS) related neuropathy but further workup showed very high levels of anti-MAG antibody titer." (PMID 30338181, 2018).
neuropathy (continued). "A causal relationship between anti-myelin-associated glycoprotein (MAG) IgM antibodies, identified in half of the patients, and neuropathy has been established." (PMID 29399323, 2017). "The electrophysiological findings in five patients with confirmed antibodies indicated the presence of neuropathy, but only one, with anti‐MAG antibodies, had clinically obvious polyneuropathy." (PMID 27186442, 2016). "Four patients who had concordant nerve conduction and neuropathological findings suggestive of anti-MAG neuropathy had low titers of anti-MAG antibodies (1111–8663 BTU) but positive SGPG antibodies." (PMID 26065001, 2015). "This latter feature corresponding to deposits of the monoclonal IgM on myelin sheath distinguishes pathologically anti-MAG neuropathy from chronic inflammatory demyelinating polyradiculoneuropathy (CIDP)." (PMID 26065001, 2015). "Of note, anti-MAG antibodies were above 10000 BTU in 32 (86%) of the 37 patients with NCS suggestive of anti-MAG neuropathy (p < 0.05)." (PMID 26065001, 2015). "Conversely, the majority of patients with neurophysiological studies consistent with anti-MAG neuropathy and high titers of anti-MAG antibodies had a positive indirect immunofluorescence study." (PMID 26065001, 2015). "These 4 patients, who had electrodiagnostic testing suggestive of anti-MAG neuropathy and typical WML for 3 of them, had positive SGPG antibody testing." (PMID 26065001, 2015). "In the present study, we show that anti-MAG neuropathy is indeed a heterogeneous disorder as demonstrated by careful clinical, electrophysiological, and neuropathological analysis." (PMID 26065001, 2015). "This study clearly demonstrates that anti-MAG neuropathy is indeed a relatively heterogeneous entity and that this heterogeneity can be found at the clinical, neurophysiological, and pathological levels." (PMID 26065001, 2015). "On semi-thin sections through EM, we observed chronic demyelinating lesions and characteristic widening of myelin lamellae (WML) as described in anti-MAG neuropathies." (PMID 25621682, 2015). "DADS associated with positivity for anti-MAG antibodies, termed anti-MAG neuropathy, is separated from CIDP according to the 2010 EFNS/PNS guidelines." (PMID 25105500, 2014). "Although the combined administration of IVIg and interferon-β-1a is effective in patients with acute inflammatory demyelinating polyneuropathy, it is not obvious that this combined therapy is effective in patients with MAG-related neuropathy." (PMID 23286283, 2013). "It is well established that Cx32/GJB1‐null mice (CMT1X model) exhibit CMT‐like neuropathy with slowed conduction and progressive myelin defects, whereas MAG‐null mice display related myelin and functional abnormalities and have been suggested to mimic aspects of HNPP." (PMID 41400104, 2026). "One recent study identified ≥1500 BTU as an optimal diagnostic threshold (78% sensitivity, 96% specificity), and ≥10 000 BTU as a highly specific threshold (100% specificity) for typical anti-MAG antibody neuropathy, although the control cohort included only 72 CIDP patients." (PMID 40748018, 2025). "Given that MRC scale does not account for the distal motor sectors that are most affected in anti-MAG neuropathy, and since its expression is typically sensory dominant, it may not accurately reflect clinical impairment in this condition." (PMID 41031196, 2025). "Results: 8 male patients were enrolled ‐ 4 CIDP and 4 anti‐MAG neuropathy patients." (PMID 40542608, 2025). "None of the 17 subjects in the 2015 study experienced VTE events, despite a VTE prophylaxis algorithm identical to ours, thus raising the question of whether the high VTE risk in our study was a disease‐specific concern unique to anti‐MAG neuropathy patients." (PMID 38015467, 2024).